SPP1 (secreted phosphoprotein 1)
Diseases named in the same sentence as SPP1 in open-access papers (continued):
Sharing a sentence is not in itself a finding about the gene and the disease.
Alzheimer disease (45 papers, 2016 to 2026). A progressive, neurodegenerative disease characterized by loss of function and death of nerve cells in several areas of the brain leading to loss of cognitive function such as memory and language. "Osteopontin (SPP1) is a multifunctional matricellular glycoprotein, and it is notably upregulated during the inflammation associated with Alzheimer’s disease and other neurodegenerative conditions." (PMID 35447931, 2022). "Moreover, SPP1 was found to be upregulated and act as an essential modulator of macrophage phenotypes and their ability to clear pathogenic beta-amyloid forms in mice models of Alzheimer’s disease." (PMID 33375642, 2020). "A report in Nature Neuroscience showed that SPP1 promotes synaptic phagocytosis by microglia in Alzheimer’s disease (AD)." (PMID 40867844, 2025). "For example, APOE and SPP1 mRNA participate in lipid metabolism and are related to Alzheimer’s disease." (PMID 38892402, 2024). "Another study on Alzheimer's disease indicated that Spp1 derived from perivascular macrophages promotes microglial phagocytosis of synapses." (PMID 39272194, 2024). "Other studies reported that urine SPP1 was a potential biomarker for Alzheimer's disease and kidney injury." (PMID 37696527, 2023). "APOC1 and SPP1, prominent in cluster 3, are two of the genes characterizing the disease-associated microglia (DAM) subtype of microglia found in animal models of Alzheimer’s disease and other conditions." (PMID 36466814, 2022). "In the brain, Alzheimer’s disease and memory-related genes (Camk2n1, Apod, and Serpina3n), and immune-response-related genes (Spp1, CD68, GFAP, Mpeg, Ddx3y, Lyz2, CTSZ, Tyrobp, C4b, and C1qa), were selected for mRNA qPCR analysis in adenine-induced CKD mice." (PMID 35447931, 2022). "SPP1 (secreted phosphoprotein 1) and NRXN3 (neurexin 3) are already known to be associated with Alzheimer’s disease." (PMID 30220890, 2018). "Research by Sebastiaan De Schepper and colleagues in an Alzheimer’s disease model suggests that extracellular SPP1 may also regulate synaptic phagocytosis by microglia via TGF-β signaling." (PMID 41000385, 2025). "Furthermore, we suggest that targeted drug therapies for these molecular links, mainly focusing on SPP1, may be a promising approach for treating both Alzheimer’s disease and metabolic syndrome." (PMID 38809924, 2024). "The role of elevated SPP1 in vascular inflammation and endothelial dysfunction provides insight into how blood-brain barrier dysfunction may contribute to neuroinflammation and the development of Alzheimer’s disease (AD)." (PMID 38809924, 2024). "Distinct immune markers were found to differentiate FTD from Alzheimer’s disease (AD) and amyotrophic lateral sclerosis (ALS), with GFAP, SPARC, and SPP1 varying between FTD and AD and IL-15, HERV-K, NOD2, and CHIT1 differing between FTD and ALS." (PMID 40305176, 2025). "SPP1, CD44, IGF1, and FLT1 were identified as crucial molecules in the main cluster of Alzheimer’s disease and metabolic syndrome." (PMID 38809924, 2024). "Ten DEGs, including IGF1, VEGFC, RAPGEF3, PIK3CA, Akt3, ITGB3, ITGA11, SPP1, NOS1, and ATP6V0B, were selected from Rap1, oxidative phosphorylation, and Alzheimer’s disease signaling pathways." (PMID 34359260, 2021). "Expression of neuroprotective genes Igf1, Gpnmb and Spp1 is increased in microglia from both NPC1 and Alzheimer disease mouse models." (PMID 32731618, 2020). "Enrichment analysis by the DAVID dataset was employed and highlighted the SPP1 as a novel target, with its receptor CD44 playing a significant role in the inflammatory cascade and disruption of insulin signaling, contributing to the neurodegenerative aspects of Alzheimer’s disease." (PMID 38809924, 2024). "Similarly, OPN (SPP1) is involved in microglia activation pathway and has been found up-regulated in EAE and WM active lesions of MS patients, as well as in an Alzheimer’s disease model." (PMID 32811567, 2020).
heart failure (43 papers, 2011 to 2026). Inability of the heart to pump blood at an adequate rate to meet tissue metabolic requirements. "In the context of cardiac fibrosis associated with heart failure, SPP1+ macrophages expressing TREM2 and CD9 showed an increased presence and were strongly correlated with fibrotic changes in the heart tissue." (PMID 40072075, 2025). "Increased expression of SPP1 has been implicated in VC development, as well as coronary artery disease and heart failure." (PMID 33101359, 2020). "The mechanisms underlying SPP1+ macrophage function in cardiac fibrosis provide a foundation for innovative therapies aimed at mitigating pathological remodeling and improving outcomes in patients with heart failure." (PMID 40072075, 2025). "Previous studies revealed that SPP1 served as an effective prognostic or diagnostic biomarker in circulatory system diseases such as ischemic stroke, stable coronary artery disease, heart failure and peripheral artery disease." (PMID 38426091, 2024). "In human heart failure, single-cell transcriptomic profiling revealed a marked expansion of SPP1+ macrophages, co-expressing markers such as FN1 and TREM2, and occupying fibrotic niches where they orchestrate ECM remodeling through CXCL4 signaling." (PMID 40900730, 2025). "Progeny pathway analysis revealed a notable downregulation of the MAPK signaling pathway in SPP1+ LAMs compared to other macrophage subsets in the context of murine ischemic reperfusion injury and human heart failure." (PMID 38449872, 2024). "Transcript levels of several established biomarkers, including Spp1, Sfrp1, Sfrp2, Tnc, Vim, Mmp9, and Tnfrsf1a, and several inflammatory markers that are known to be activated in heart failure, such as Cd44, Cd83, Ccl7, Irf7, and Nr4a2, were upregulated in the Myh6-McmTamDspfl/fl cardiomyocytes." (PMID 40608429, 2025). "They confirm expansion of SPP1+ macrophages in human heart failure and chronic kidney disease." (PMID 36807143, 2023). "Finally, we confirm that Spp1 macrophages expand in both human chronic kidney disease and heart failure." (PMID 36807143, 2023). "Indeed, reference mapping of MPC from human heart failure to human CKD confirmed that cardiac SPP1+ macrophages best correspond to renal SPP1+ macrophages, highlighting a conserved phenotype of profibrotic macrophage activation across organs." (PMID 36807143, 2023). "By analyzing the heart failure-related GSE47495 dataset and performing gene ontology (GO) functional enrichment analysis, we obtained histone lysine methyltransferase SUV39H1 and secreted phosphoprotein 1 (SPP1) as two molecules implicated in the oxidative stress and inflammation processes." (PMID 36193085, 2022). "In the si-SUV39H1+si-SPP1 group, 1 rat died from infection and 1 from heart failure." (PMID 36193085, 2022). "THBS1, SPP1 and LGR1 were previously associated with cardiomyocyte fibrosis, and heart failure." (PMID 35052347, 2021). "Additionally, SPP1+ macrophages expand in both chronic kidney disease and heart failure in humans." (PMID 40072075, 2025). "In addition, macrophages and activated lymphocytes highly express SPP1 in atherosclerotic plaques, which promote the formation of fatty streaks and plaque development, and SPP1 is also involved in the calcification process of atherosclerotic plaques and results in heart failure." (PMID 38919629, 2024). "Finally, to investigate whether SPP1+ macrophages characterize a profibrotic macrophage subset in human heart failure, we again scored MPC based on their ECM regulator scores." (PMID 36807143, 2023). "Translating our findings to human disease, we confirmed expansion of profibrotic SPP1+ macrophages in both human CKD and heart failure." (PMID 36807143, 2023). "Additionally, platelet-derived CXC chemokine ligand 4 (CXCL4) is required for SPP1+ macrophage activation and organ fibrosis, and an expansion in SPP1+ macrophages of patients with CKD and those with heart failure has also been found." (PMID 38919629, 2024).
lymph node metastasis (43 papers, 2012 to 2025). "The analysis of the two cohorts revealed a potential RNA-immune cell axis (lncRNA AC037441/SPP1-macrophage) associated with early lymph node metastasis." (PMID 34646827, 2021). "The expression level of SPP1 in PCa was positively associated with clinical stages and lymph node metastasis." (PMID 34721759, 2021). "In addition, the expression levels of SPP1 have been associated with clinical stages, lymph node metastasis, and disease-free survival in PCa." (PMID 37239316, 2023). "SPP1 is also associated with clinical lymph node metastasis." (PMID 36688087, 2023). "Our results suggested that macrophage-related SPP1 expression may be a crucial risk indicator for early lymph node metastasis in LUAD." (PMID 34646827, 2021). "Notably, SPP1 in the blood, as detected by enzyme-linked immunosorbent assay (ELISA) showed a superior predictive capability for early lymph node metastasis [area under the curve (AUC) = 0.74]." (PMID 34646827, 2021). "And positively associations of SPP1 expression with TNM stage, lymph node metastasis, and invasion depth were observed." (PMID 36266702, 2022). "S100P-SPP1 + iCCApps had less lymph node metastasis, larger tumor volume, and better prognosis than S100P + SPP1− iCCAphl." (PMID 35347134, 2022). "In the GSE43580 cohort, SPP1 was highly expressed in the lymph node metastasis group (p < 0.01), and the correlation between SPP1 and M0 was also analyzed (r = 0.35, p = 0.09)." (PMID 34646827, 2021). "Patients with high macrophage infiltration were showed to present the significant enrichment of EMT pathway, and SPP1, an EMT hallmark gene, was identified to be significantly associated with macrophage infiltration and lymph node metastasis." (PMID 34646827, 2021). "In conclusion, we revealed the potential role of macrophages in lymph node metastasis and identified the macrophage-related gene SPP1 as a potential biomarker for early lymph node metastasis in LUAD." (PMID 34646827, 2021). "The SPP1 is most expressed in grade N3 lymph node metastasis compared to N0, N1, and N2." (PMID 36688087, 2023). "To explore the clinical phenomenon in which some LUAD patients develop lymph node metastasis at a very early T-stage, we revealed the crucial roles played by macrophages in lymph node metastasis and identified macrophage-related SPP1 as a potential biomarker for early metastasis in lung cancer." (PMID 34646827, 2021). "In addition, the predictive efficacy of SPP1 detection in plasma for early lymph node metastasis was evaluated." (PMID 34646827, 2021). "Subsequently, the EMT hallmark gene SPP1, encoding secreted phosphoprotein 1 (SPP1), was identified to be significantly correlated with macrophage infiltration and M2 polarization, and was determined to be a key risk indicator for early lymph node metastasis." (PMID 34646827, 2021). "The predictive efficiency of SPP1 for early lymph node metastasis was evaluated in four cohorts." (PMID 34646827, 2021). "We do not know the splice variants of SPP1 in non-metastatic oral cancer and metastatic oral cancer with lymph node metastasis beside the expression difference, which deserves further investigation." (PMID 30459815, 2018). "In addition, using the survival data for the GSE68465 cohort, we demonstrated that early lymph node metastasis (p < 0.001), higher M0 infiltration (p = 0.035), and higher SPP1 expression (p = 0.023) were significantly associated with the poor prognosis among patients with Stage-T1 LUAD." (PMID 34646827, 2021). "The proportion of patients with high SPP1 mRNA expression was unequal in different TNM stage groups (p = 0.029), lymph node metastasis groups (p = 0.006), and invasion depth groups (p = 0.024)." (PMID 36266702, 2022). "In the progression of lymph node metastasis of LUAD, the higher the N stage, the higher the SPP1 expression level." (PMID 32595698, 2020).
lymph node metastasis (continued). "Moreover, the high SPP1 expression was closely related to clinical features, such as TNM stage, invasion depth, and lymph node metastasis." (PMID 36266702, 2022). "First, SPP1 was identified through the expression level analysis of 19 genes comparing the lymph node metastasis group with the non-metastatic group in both TCGA (p < 0.05) and GSE68465 cohorts (p < 0.05)." (PMID 34646827, 2021). "In addition, we found through ELISA that the serum level of SPP1 in patients with penile cancer accompanied by lymph node metastasis was significantly higher than that in patients with penile cancer without lymph node metastasis." (PMID 38111044, 2023).
coronary artery disease (39 papers, 2006 to 2026). "Elevated serum SPP1 levels confer an increased risk for plaque vulnerability in patients with coronary artery disease." (PMID 38426091, 2024). "Clinically, Elevated serum SPP1 levels have been linked to the presence and severity of coronary artery disease." (PMID 38426091, 2024). "One review reported that high plasma SPP1 was related to the increased risk of major adverse cardiac events and to the extent and presence of coronary artery disease." (PMID 31449494, 2019). "However, further studies are warranted to elucidate the specific mechanism of SPP1 in the regulation of vulnerable plaque formation in patients with coronary artery disease." (PMID 38426091, 2024). "A study of 120 subjects conducted in 2000 first proposed that there was a positive relationship between SPP1 and coronary artery disease, and SPP1 might be a potential biomarker to identify patients with or at risk for ACS." (PMID 33224526, 2020). "We also performed ELISA to investigate the corresponding proteins levels of selected genes and showed that serum levels of SPP1, CD36, ATP6V0D2, CHI3L1, MYH11, and BDNF were differentially expressed in patients with coronary heart disease compared with healthy subjects." (PMID 31682178, 2019).
systemic lupus erythematosus (36 papers, 2007 to 2026). An autoimmune multi-organ disease typically associated with vasculopathy and autoantibody production. "The diseases associated with SPP1 include pediatric systemic lupus erythematosus and dentin dysplasia, and its related pathways are the integrin and ERK signaling pathways." (PMID 38612943, 2024). "The variant driving this association at SPP1, a splice-site variant (rs139555315, 4:88901197, MAF = 1.54E-03), was reported to be associated with pediatric systemic lupus erythematosus." (PMID 35385482, 2022). "While this experiment is beyond the scope of the present study, we hope to assess SPP1 gene and protein expression in male and female lupus patients in future." (PMID 18335026, 2008). "Two SNPs (rs1126772 and rs9138) in the 3′ UTR in the SPP1 gene were associated with high levels of SPP1 and elevated risk of developing autoimmune/lymphoproliferative syndrome (ALPS), a disorder which leads to an autoimmune pattern similar to lupus prone strains of mice." (PMID 18335026, 2008).
Hypertension (35 papers, 2011 to 2026). The presence of chronic increased pressure in the systemic arterial system. "Elevated SPP1 levels may also be linked to vascular stiffness and hypertension." (PMID 38809924, 2024). "NAIs attenuate nicotine-induced endothelial dysfunction in hypertension by inhibiting AP1-mediated FN1 and SPP1 activation, providing novel insights for smoking-associated cardiovascular risk." (PMID 40722963, 2025). "Our findings identify FN1 and SPP1 as pivotal molecular targets linking endothelial dysfunction to hypertension, offering novel therapeutic insights for the prevention and treatment of cardiovascular diseases associated with nicotine exposure." (PMID 40722963, 2025). "Spp1 in VAT may emerge as a promising therapeutic target for hypertension, deserving further investigation." (PMID 38689862, 2024). "Interestingly, blocking Ang-II inhibits Spp1 expression in non-infarcted myocardium of post-MI hearts and olmesartan, which is an Ang II receptor blocker, significantly decreases plasma OPN levels in patients with hypertension." (PMID 34356671, 2021).
liver disease (35 papers, 2012 to 2025). "Interestingly, expression of Spp1, the gene encoding osteopontin and associated with more advanced liver disease progression, seemed to be decreased in multiple clusters including monocytes, transitioning monocytes, C-LAMs, and LAMs in Lrat-Mpc2-/- mice compared with WT mice." (PMID 40239806, 2025). "On the other hand, increased numbers of SPP1+ macrophages in pathological conditions have led to their consideration as a potential biomarker of liver disease." (PMID 40395129, 2025). "SPP1 promotes inflammatory responses, cellular activation, proliferation, and migration, and inhibits autophagy in liver disorders." (PMID 39013959, 2024). "It was worth noting that SPP1 and TGFB1 genes are not only associated with congenital (and childhood) liver disease, but also with adult liver disease." (PMID 34095116, 2021). "We next analyzed gene expression levels of osteopontin (Spp1), a multifunctional protein involved in liver diseases." (PMID 30818874, 2019). "The downregulation of SPP1, a multifunctional protein known to promote inflammatory responses in liver diseases, aligns with the observed suppression of the hedgehog signaling pathway, consistent with the role of osteopontin as a downstream target of hedgehog pathway activation." (PMID 41012748, 2025). "Additionally, our results indicate that SPP1 has a key role in liver disease, where it communicates with T cells expressing CD44." (PMID 38768139, 2024). "Thus, to obtain functional insight into Spp1 in the end-stage liver disease HCC, we analyzed the mRNA level using the human cancer microarray database Oncomine." (PMID 22281153, 2012). "We found significant fold changes for SPINK1, LEF1, TSPAN8, SPP1, OR2I1P and PTGFRN comparing HH-HCC with HH-liver disease and normal liver (p<0.05, one-way Anova)." (PMID 23527199, 2013).
chronic kidney disease (33 papers, 2013 to 2026). Impairment of the renal function secondary to chronic kidney damage persisting for three or more months. "A cohort study that analyzed the effect of SPP1 polymorphisms in CVE in patients with chronic kidney disease found that the group of patients with cardiovascular events (CVE) had a higher incidence of atherosclerotic plaque and higher OPN levels at baseline." (PMID 36359759, 2022). "Similarly, PBXIP1 is associated with renal fibrosis and chronic kidney disease, while SPP1 is related to damage in renal tubules." (PMID 39086896, 2024). "For example, SPP1 is a key inflammatory player across multiple diseases and has prognostic and therapeutic potential in chronic kidney disease." (PMID 40114603, 2025). "An additional investigation revealed the significant function of SPP1 in modulating ECM dynamics in chronic kidney disease, accompanied by sarcopenia." (PMID 41293726, 2025). "Research in single-cell transcriptomics has identified SPP1 as a crucial hub molecule in polyploid cells during the transition from acute kidney injury to chronic kidney disease, involving the EMT mechanism." (PMID 41293726, 2025). "A population of profibrotic macrophages marked by expression of Spp1, Fn1 and Arg1 (termed Spp1 macrophages) expand in human chronic kidney disease." (PMID 38276550, 2024). "SPP1 affects the occurrence, development, and prognosis of CKD by affecting ECM dynamics, and is also important in the process of acute kidney injury to chronic kidney disease (AKI-CKD) transformation." (PMID 41293726, 2025). "Furthermore, SPP1 is integral to the progression from acute kidney injury to chronic kidney disease (AKI-CKD)." (PMID 41293726, 2025). "Furthermore, in mice lacking the OPN gene (Spp1−/−), chronic kidney disease resulted in the deposition of significantly larger urinary stone deposits." (PMID 40944007, 2025).